CLCA3P (chloride channel accessory 3, pseudogene )
Synonyms: CLCA3
Gene: Long non-coding RNA gene on chromosome 1 (86,634,273 to 86,655,376, forward strand). Ensembl gene ENSG00000291014.
Diseases named in the same sentence as CLCA3P in open-access papers:
CLCA3P is named in the same sentence as 2 diseases in open-access papers, as found by Europe PMC text mining. Sharing a sentence is not in itself a finding about the gene and the disease. The quoted sentences say what the papers report.
glioma (2 papers, 2019 to 2022). A benign or malignant brain and spinal cord tumor that arises from glial cells (astrocytes, oligodendrocytes, ependymal cells). "Six pseudogenes (SP3P, ANXA2P3, PTTG3P, LPAL2, CLCA3P, and TDH) were reported to be associated with overall survival in glioma." (PMID 36333286, 2022). "A prior report that constructed another signature with six pseudogenes (SP3P, ANXA2P3, PTTG3P, LPAL2, CLCA3P, and TDH) for prediction of glioma patient survival." (PMID 31681595, 2019).
CLCA3P also shares sentences with these, for which no sentence is quoted: infection (1 paper).